GAA (alpha glucosidase)
Diseases named in the same sentence as GAA in open-access papers (continued):
Sharing a sentence is not in itself a finding about the gene and the disease.
lysosomal storage disorder (35 papers, 2012 to 2026). "Pompe disease is an autosomal recessive lysosomal storage disorder caused by deficiency of acid alpha-glucosidase (GAA), leading to pathological glycogen accumulation in multiple tissues." (PMID 41783848, 2026). "BACKGROUND: Pompe disease (PD), caused by a deficiency in acid α-glucosidase (GAA), is a lysosomal storage disorder." (PMID 41742217, 2026). "Pompe disease is a rare, inherited, multisystemic and progressive lysosomal disorder caused by pathogenic variants in the acid α-glucosidase (GAA) gene that lead to deficiency of GAA enzyme activity." (PMID 39775064, 2025). "GSD type II (known as Pompe disease), also classified as lysosomal storage disease, is caused by mutations in the GAA gene resulting in a deficiency of alpha-1-4-glucosidase (acid maltase) causing marked accumulation of glycogen in lysosomes." (PMID 37601653, 2023). "Pompe disease is a lysosomal storage disorder with impaired glycogen degradation caused by a deficiency of the enzyme acid α-glucosidase (GAA)." (PMID 37765007, 2023). "Pompe disease (OMIM#232300) is an autosomal recessive lysosomal storage disorder caused by mutations in the GAA gene." (PMID 34639227, 2021). "Pompe disease is an inherited lysosomal storage disorder caused by acid alpha-glucosidase (GAA) enzyme deficiency, resulting in muscle and neuron intralysosomal glycogen storage." (PMID 33073019, 2020). "Pompe disease (PD) is a lysosomal storage disease (LSD) caused by mutations in GAA which encodes the enzyme acid maltase (alpha 1,4-glucosidase)." (PMID 32316520, 2020). "Pompe disease (PD) is an autosomal recessive, lysosomal storage disease due to a mutation of the acid α-glucosidase (GAA) gene." (PMID 29523196, 2018). "Pompe disease (OMIM 232300) or glycogenosis type 2 is a lysosomal storage disease characterized by a mutation of the acid α-glucosidase (GAA) gene." (PMID 29523196, 2018). "Acid alpha-glucosidase (GAA, also called acid maltase) deficiency (Pompe disease) was the first identified lysosomal storage disease." (PMID 29095275, 2017). "However, paucimannosidic (MM) N-glycans facilitate the uptake of proteins via mannose receptors, as shown for AGAL and potentially for other lysosomal storage disease-associated proteins such as GAA." (PMID 40718020, 2025). "Pompe disease (glycogen storage disease type II, OMIM #232300) is a lysosomal storage disorder caused by a deficiency of the enzyme acid alpha-glucosidase (GAA), which leads to lysosomal glycogen accumulation mainly in muscle tissue, but also in the central nervous system." (PMID 36480052, 2023). "When compared to other lysosomal storage diseases, Pompe disease requires larger quantities of functional recombinant human GAA protein distributed throughout the body, including the CNS." (PMID 35203513, 2022). "Pompe disease is a lysosomal storage disorder in which acid alpha-glucosidase (GAA) is deficient or absent." (PMID 25183957, 2014). "Lysosomal storage disease genes include GRN, GPNMB, GAA, and CHIT1 which, according to STRING analyses, interact with CD68, CD63, and TLR3, and are known to have lysosomal membrane function." (PMID 37422510, 2023).
glycogen storage disease (20 papers, 2013 to 2026). "Pompe disease is a glycogen storage disorder caused by a deficiency in Lysosomal acid-a-Glucosidase, which is encoded by the GAA gene and leads to intra-lysosomal glycogen accumulation." (PMID 41511290, 2025). "For diagnostic biopsies, one biopsy showed morphological signs of glycogen storage disease and an alfa-1,4-glucosidase deficiency (confirmed with a mutation in the GAA gene)." (PMID 41464103, 2025). "Subsequently, we applied sABE to introduce mutations related to glycogen storage disease (T1214C in GAA) and Charcot-Marie-Tooth disease (A494G in MFN2) in HEK293T cells." (PMID 37434184, 2023). "This study reported 12 Chinese patients with Glycogen storage disease and identified 18 gene variants of GAA, AGL, PHKA2 and PYGL (9 novel and 9 reported) by whole-exome sequencing." (PMID 36105079, 2022). "Pompe disease is a hereditary glycogen storage disease where a defect in the lysosomal enzyme alpha-glucosidase (GAA) leads to progressive lysosomal glycogen overload predominantly in striated muscles and motor neurons." (PMID 38129558, 2023).
Obesity (14 papers, 2007 to 2025). Accumulation of substantial excess body fat. "In the control group, T2DM participants received either placebo or other hypoglycemic agents, including metformin, insulin, and alpha‐glucosidase inhibitors, while participants with obesity received only placebo." (PMID 40887719, 2025). "This study tested if the heterozygous knockout of GAA (HetKO‐GAA) alters liver metabolism and metabolic health in mice fed a low‐fat diet or a high‐fat diet to induce obesity." (PMID 40108792, 2025). "In summary, partial inhibition of GAA is nonconsequential to liver metabolism or metabolic health in male or female mice with HFD‐induced obesity and prediabetes, suggesting that the liver produces more than enough GAA enzyme for adequate glycophagy flux." (PMID 40108792, 2025). "As discussed in this review, carbonic anhydrase inhibitors (CAIs) and alpha-glucosidase inhibitors (AGIs) are used therapeutically as anti-obesity and anti-glaucoma agents, respectively, as well as antidiabetic agents." (PMID 39339309, 2024). "Other enzymes that can be significantly involved in obesity development are alpha-amylase and alpha-glucosidase, which hydrolyze starch and carbohydrates, respectively." (PMID 36829976, 2023). "Antidiabetic and anti-obesity potential were evaluated by inhibition of alpha-glucosidase (α-GLU), advance glycation end products (AGEs) formation and pancreatic lipase." (PMID 37508324, 2023). "Inhibition of pancreatic enzymes (both lipase, and alpha-glucosidase) has been reported to be one of the drug targets for anti-obesity." (PMID 37733688, 2023). "An extract from this plant was found to act on dopaminergic cells, to inhibit the activity of glycolytic enzymes, such as alpha-glucosidase, and consequently to suppress obesity in an animal model." (PMID 36501129, 2022). "We investigated the antioxidant, alpha-glucosidase inhibitory activity, and anti-obesity effects of fruits, vegetables, and herbs." (PMID 31548839, 2019). "Miglitol is an alpha-glucosidase inhibitor (αGI) that is commonly used as an anti-diabetic drug, and there is growing evidence that it also has anti-obesity effects." (PMID 26628904, 2015). "The results showed that berberine actually increases insulin sensitivity and is capable of inhibiting alpha glucosidase, adipogenesis, and thus acts as an anti-obesity and hypoglycemic agent." (PMID 26693406, 2015). "FDA‐approved GAA inhibitors, such as acarbose or miglitol, are effective at improving insulin action and glycemic control while also being effective at reducing fatty liver in individuals with obesity and type 2 diabetes." (PMID 40108792, 2025). "The mechanisms through which polyphenols can inhibit obesity include inhibiting digestive enzymes (mainly alpha-glucosidase, pancreatic lipase, fatty acid synthase, and alpha-amylase), stimulating energy expenditure, suppressing appetite, regulating lipid synthesis, and modulation of gut microbiota." (PMID 36829976, 2023). "However, in a HFD induced obesity and prediabetes model, HetKO‐GAA is not sufficient to reduce liver glucose output and has no impact to alter glucose tolerance, suggesting that partial disruption of the GAA gene is insufficient to alter liver metabolism." (PMID 40108792, 2025).
Hypoglycemia (13 papers, 2011 to 2024). A decreased concentration of glucose in the blood. "Others have reported amelioration of post-prandial hypoglycemia with acarbose, an alpha-glucosidase enzyme inhibitor, although its effect on associated gastrointestinal disturbance remains unknown." (PMID 21569503, 2011). "Both sulfonylurea and alpha-glucosidase inhibitor were prevalent in patients of Group 4 who had a higher frequency of severe hypoglycemia." (PMID 33678721, 2022). "For example, diguanides, thiazolidinedione, and alpha glucosidase inhibitors, used for antidiabetic agents, result in renal failure, hypoglycemia, liver toxicity, abdominal distention, and abnormal weight gain." (PMID 27069493, 2016). "We then tried acarbose, an alpha-glucosidase inhibitor that interferes with carbohydrate absorption, which resolved the patient's postprandial symptoms and hypoglycemia, but she was unable to tolerate it due to gastrointestinal side effects, which are commonly seen with this medication." (PMID 22937294, 2012). "If glycemic control remains inadequate, changing the type of insulin or using medications like alpha-glucosidase inhibitors, DPP-4 inhibitors, and GLP-1RA can help lower blood glucose levels while preventing hypoglycemia." (PMID 39575003, 2024). "Among the Ins-users, the number of patients with hypoglycaemia in the ~22:00-23:00 range was significantly higher than that of patients taking alpha-glucosidase inhibitor (αGI) who were not taking αGI (P=0.015)." (PMID 38975379, 2024). "If the insulin dose is minimal, it may be possible to discontinue insulin and switch to medications such as alpha-glucosidase inhibitors, dipeptidyl peptidase-4 (DPP-4) inhibitors, and glucagon-like peptide-1 receptor agonist (GLP-1RA)to manage blood sugar levels while also preventing hypoglycemia." (PMID 39575003, 2024). "Compared to those who did not suffer from severe hypoglycemia, patients with severe hypoglycemia at baseline had higher prescriptions of various anti-glucose drugs, including sulfonylurea, meglitinide, thiazolidinedione, alpha-glucosidase inhibitor, and insulin." (PMID 33678721, 2022).
metabolic myopathy (12 papers, 2014 to 2025). A group of rare inherited disorders characterized by a deficiency of enzymes that are involved in metabolic pathways that affect muscles. "Pompe disease (PD) is an inherited, progressive, metabolic myopathy resulting from the lysosomal accumulation of glycogen due to a deficiency in the lysosomal hydrolase, acid alpha-glucosidase (GAA; EC 3.2.1.20)." (PMID 34357340, 2021). "Pompe Disease (PD) is a rare inherited metabolic myopathy, caused by lysosomal-α-glucosidase (GAA) deficiency, which leads to glycogen accumulation within the lysosomes, resulting in cellular and tissue damage." (PMID 33996274, 2021). "Pompe disease is a metabolic myopathy that is caused by deficiency of acid alpha glucosidase (GAA), a lysosomal enzyme responsible for the degradation of glycogen." (PMID 30404653, 2018). "Pompe disease is a metabolic myopathy that is caused by glycogen accumulation as a result of deficiency of the lysosomal enzyme acid alpha glucosidase (GAA)." (PMID 30404653, 2018). "Pompe's disease is a metabolic myopathy caused by a deficiency of acid alpha-glucosidase (GAA), also called acid maltase, an enzyme that degrades lysosomal glycogen." (PMID 28265479, 2017). "Pompe disease is a metabolic myopathy due to acid alpha‐glucosidase deficiency." (PMID 34606154, 2021). "Since the PD clinical signs overlap with the symptoms of other muscle disorders, GAA and other genes causing metabolic myopathies should be analysed in gene panels used for testing neuromuscular diseases, in order to identify PD patients that are potentially misdiagnosed." (PMID 32745073, 2020). "Following clinical indications, the laboratory diagnosis of the inherited metabolic myopathy, Pompe disease (PD), typically begins with demonstrating a reduction in acid alpha-glucosidase (GAA), the enzyme required for lysosomal glycogen degradation." (PMID 34357340, 2021). "Pompe Disease is an inherited metabolic myopathy characterized by abnormal glycogen storage due to lack of the enzyme acid alpha-glucosidase (GAA) in skeletal muscle lysosomes." (PMID 40558510, 2025).
Insulin resistance (9 papers, 2010 to 2026). Increased resistance towards insulin, that is, diminished effectiveness of insulin in reducing blood glucose levels. "And alpha-glucosidase inhibitors also improve atherogenic dyslipidemia, reduce insulin resistance, and lead to improved endothelial function, thus reducing cardiovascular events." (PMID 36873813, 2023). "Combined with the GO analysis results, these results suggest that the mechanism of action of RMA improves insulin resistance and glucose tolerance through influencing carbohydrate metabolism by regulating alpha-glucosidase activity." (PMID 36278175, 2022). "Rhus verniciflua ethanol extract revealed a strong alpha-glucosidase inhibitory activity, which was able to reduce weight gain and improve insulin resistance." (PMID 36501129, 2022). "The fatty acids present in the extract may enhance tissue insulin sensitivity by inhibiting alpha‐glucosidase activity, while saponins contribute to the reduction of inflammation and improvement of insulin resistance." (PMID 41549047, 2026). "Their mechanism of action mainly involves improved insulin sensitivity and insulin resistance, inhibited activity of alpha-glucosidase, antioxidant activity, anti-inflammatory, regulation of gut microbiota and activating of peroxisome proliferator-activated receptor-γ." (PMID 38099180, 2023). "While no medication specifically targets insulin resistance, several antidiabetic drugs, including insulin sensitizers, insulin secretagogues, and alpha-glucosidase inhibitors, have been utilized to improve insulin resistance." (PMID 38053837, 2023). "The potential benefits of optimal egg-derived protein might be due to its metabolites, such as alpha-glucosidase inhibitory peptides, ACE inhibitory peptides, DPP-4 inhibitory peptides, which showed effects on the improvement of glucose tolerance, postprandial hyperglycemia, and insulin resistance." (PMID 35022027, 2022).
heart failure (6 papers, 2019 to 2024). Inability of the heart to pump blood at an adequate rate to meet tissue metabolic requirements. "Pompe disease, a metabolic disorder defined by a mutation in the acid alpha-glucosidase (GAA) gene, results in heart failure in a majority of affected patients by 18 months of age." (PMID 30988697, 2019). "Other medication classes, including DPP-4 inhibitors; insulin (glargine); alpha-glucosidase inhibitors; glinides; D2-dopamine agonists; GLP-1 agonist; and sulfonylurea are neutral to heart failure outcomes." (PMID 34926000, 2021).
hypertrophic cardiomyopathy (5 papers, 2019 to 2026). A condition in which the myocardium is hypertrophied without an obvious cause. "Glycogen storage disease type II (GSD II), also known as Pompe disease, is an autosomal recessive inherited metabolic disorder caused by a deficiency of acid alpha-glucosidase (GAA); it manifests as muscle weakness, hypertrophic cardiomyopathy, and respiratory failure." (PMID 31439017, 2019). "Research into Pompe disease has revealed that mutations in the acid alpha-glucosidase (GAA) gene cause lysosomal glycogen accumulation, resulting in mitochondrial structural abnormalities and energy metabolism disorders, ultimately leading to hypertrophic cardiomyopathy and HF." (PMID 40734976, 2025). "A five-year-old girl with hypertrophic cardiomyopathy, muscle weakness, recurrent respiratory tract infections, elevated CK levels, and low alpha-glucosidase enzyme activity was referred to the metabolism department." (PMID 41890542, 2026). "In the most severe classic infantile form of Pompe disease, GAA enzyme activity is virtually absent and symptoms manifest shortly after birth, consisting of generalized skeletal muscle weakness and a hypertrophic cardiomyopathy." (PMID 36111639, 2023).
myocardial infarction (5 papers, 2014 to 2024). Gross necrosis of the myocardium, as a result of interruption of the blood supply to the area, as in coronary thrombosis. "The trial ABC (Alpha-glucosidase-inhibitor Blocks Cardiac Events in Patients with Myocardial Infarction and Impaired Glucose Tolerance) was terminated after a two-year period due to total lack of difference between the 2 groups, in terms of CV outcomes." (PMID 29270438, 2017). "In a meta- analysis of 7 acarbose studies (an alpha-glucosidase inhibitor which reduces glucose absorption) 1 hour postprandial glucose was reduced by 1.6 mmol/L and 2 h glucose by 2.2 mmol/l while HbA1c was reduced by 0.6% and myocardial infarctions were reduced by 64%." (PMID 25343850, 2014).
breast carcinoma (4 papers, 2019 to 2025). "The cytotoxic effect of GaA on Hela cells and GaAD19 on human cervical cancer cells, human liver cancer cells, human breast cancer cells and other nine tumor cell lines were studied using a CCK-8 assay." (PMID 41399789, 2025).
cardiomyopathy (4 papers, 2014 to 2021). A disease of the heart muscle or myocardium proper. "TTN, GAA, LAMA2 and MYBPC3 harbored the most variants in the three subgroups which confirm the high impact of these genes in complex pathogenesis of cardiomyopathies and VT demonstrated in previous studies." (PMID 33552729, 2021). "TTN, GAA, LAMA2, and MYBPC3 contained the most variants in the three subgroups which confirm the impact of these genes in the complex pathogenesis of cardiomyopathies and VT." (PMID 33552729, 2021). "Enzyme replacement therapy using recombinant human GAA (rhGAA) has proven beneficial in addressing several aspects of the disease such as cardiomyopathy and aberrant motor function." (PMID 25350581, 2014). "Variant c.1445C > T maps to the catalytic GH31 domain of the GAA protein and was found in patients with symptom onset below 12 years of age and without cardiomyopathy in a global population." (PMID 31931849, 2020).
Gaucher disease (4 papers, 2021 to 2025). Gaucher disease (GD) is a lysosomal storage disorder encompassing three main forms (types 1, 2 and 3), a fetal form and a variant with cardiac involvement (Gaucher disease - ophthalmoplegia - cardiovascular calcification or Gaucher-like disease). "ABG, ASM, GALC, IDUA, and GAA are lysosomal enzymes with reduced activity in Gaucher disease, Nimann-Pick disease, Krabbe disease, MPS-I, and Pompe disease, respectively." (PMID 35419325, 2022).
Impaired glucose tolerance (4 papers, 2014 to 2024). An abnormal resistance to glucose, i.e., a reduction in the ability to maintain glucose levels in the blood stream within normal limits following oral or intravenous administration of glucose. "Alpha glucosidase inhibitors could inhibit the absorption of carbohydrates from the gut and are used in the treatment of patients with T2D or impaired glucose tolerance." (PMID 25396726, 2014).
Infantile-onset Pompe disease (4 papers, 2019 to 2021). "Infantile-onset Pompe Disease (IOPD) is a fatal autosomal recessive glycogen storage disorder caused by a deficiency of the enzyme acid alpha-glucosidase (GAA), which breaks down lysosomal glycogen." (PMID 34220802, 2021). "Infantile-onset Pompe disease (IOPD) is a glycogen storage disease caused by a deficiency of acid alpha-glucosidase (GAA)." (PMID 34220802, 2021). "Infantile-onset Pompe disease (IOPD) is a life-threatening multi-organ disease caused by an inborn defect of lysosomal acid α-glucosidase (GAA), which can degrade glycogen into glucose." (PMID 31850350, 2019).
coronary heart disease (3 papers, 2021 to 2024). "The Acarbose Cardiovascular Evaluation (ACE) trial assessed the effects of acarbose, an alpha‐glucosidase inhibitor, in 6522 patients with coronary heart disease (CHD) and IGT from 176 hospital outpatient clinics in China." (PMID 37915263, 2024).
Danon disease (3 papers, 2023 to 2025). A lysosomal glycogen storage disease characterized by severe cardiomyopathy and variable degrees of muscle weakness, frequently associated with intellectual deficit. "Pompe disease linked to GAA (acid alpha-glucosidase) gene variations, Danon disease associated with LAMP2 (lysosomal associated membrane protein 2) gene variations, and McArdle disease caused by PYGM (muscle glycogen phosphorylase) gene variations all exhibit defective glycogen catabolism." (PMID 40868246, 2025).